DACT1 (dishevelled binding antagonist of beta catenin 1)
Description:
Involved in regulation of intracellular signaling pathways during development. Specifically thought to play a role in canonical and/or non-canonical Wnt signaling pathways through interaction with DSH (Dishevelled) family proteins. The activation/inhibition of Wnt signaling may depend on the phosphorylation status. Proposed to regulate the degradation of CTNNB1/beta-catenin, thereby modulating the transcriptional activation of target genes of the Wnt signaling pathway. Its function in stabilizing CTNNB1 may involve inhibition of GSK3B activity. Promotes the membrane localization of CTNNB1. The cytoplasmic form can induce DVL2 degradation via a lysosome-dependent mechanism; the function is inhibited by PKA-induced binding to 14-3-3 proteins, such as YWHAB. Seems to be involved in morphogenesis at the primitive streak by regulating VANGL2 and DVL2; the function seems to be independent of canonical Wnt signaling and rather involves the non-canonical Wnt/planar cell polarity (PCP) pathway (By similarity). The nuclear form may prevent the formation of LEF1:CTNNB1 complex and recruit HDAC1 to LEF1 at target gene promoters to repress transcription thus antagonizing Wnt signaling. May be involved in positive regulation of fat cell differentiation. During neuronal differentiation may be involved in excitatory synapse organization, and dendrite formation and establishment of spines.
Synonyms: hDPR1; DPR1; DAPPER1; THYEX3; DAPPER; FRODO; TBS2
Tractability: No criterion of Open Targets' tractability assessment is met for any kind of drug.
Gene: Protein-coding gene on chromosome 14 (58,633,967 to 58,648,321, forward strand). Ensembl gene ENSG00000165617.
Subcellular location: Cytoplasm; Nucleus; Synapse
Subcellular location (Human Protein Atlas): Nucleoplasm
Pathways (Reactome):
Signal Transduction: Degradation of DVL
Gene Ontology:
Molecular function: beta-catenin binding; histone deacetylase binding; protein binding; protein kinase A binding; RNA polymerase II-specific DNA-binding transcription factor binding; transcription regulator inhibitor activity; delta-catenin binding; protein kinase C binding
Biological process: negative regulation of beta-catenin-TCF complex assembly; negative regulation of canonical Wnt signaling pathway; negative regulation of G1/S transition of mitotic cell cycle; negative regulation of JNK cascade; negative regulation of transcription by RNA polymerase II; negative regulation of Wnt signaling pathway; neural tube development; positive regulation of canonical Wnt signaling pathway; positive regulation of protein catabolic process; positive regulation of Wnt signaling pathway; regulation of canonical Wnt signaling pathway; regulation of nodal signaling pathway; regulation of protein stability; embryonic hindgut morphogenesis; regulation of Wnt signaling pathway, planar cell polarity pathway; regulation of postsynapse organization
Cellular component: beta-catenin destruction complex; cytoplasm; nucleoplasm; nucleus; cytosol; glutamatergic synapse; postsynapse; synapse
Genetic constraint (gnomAD): Loss-of-function variants: 12 observed, 27.66 expected, observed/expected ratio (o/e) 0.43, 90% interval 0.28 to 0.7. The upper end of that interval is the gene's LOEUF score, 0.7, which puts it in group 2 of 6, group 1 being the genes least tolerant of losing a copy. Missense variants: 1,012 observed, 946.22 expected, observed/expected ratio (o/e) 1.07, 90% interval 1.01 to 1.13. Synonymous variants: 465 observed, 407.71 expected, observed/expected ratio (o/e) 1.14, 90% interval 1.06 to 1.23.
Homologues: Orthologues: chimpanzee DACT1 (99% identical), macaque DACT1 (97% identical), rabbit DACT1 (84% identical), pig DACT1 (82% identical), mouse Dact1 (81% identical), rat Dact1 (80% identical), dog DACT1 (79% identical), tropical clawed frog dact1 (63% identical), guinea pig DACT1 (53% identical), zebrafish dact1 (32% identical). Paralogues in human: DACT3 (24% identical), DACT2 (23% identical).
Diseases named in the same sentence as DACT1 in open-access papers:
DACT1 is named in the same sentence as 69 diseases in open-access papers, as found by Europe PMC text mining. Sharing a sentence is not in itself a finding about the gene and the disease. The quoted sentences say what the papers report.
hepatocellular carcinoma (12 papers, 2009 to 2025). A malignant tumor that arises from hepatocytes. "On the other hand, HDPR1 (DACT1) was downregulated by DNA methylation in breast or hepatocellular carcinoma and its downregulation was associated with poor prognosis in gastric and non-small cell lung cancers." (PMID 27553089, 2017). "Human Dpr1/DACT1 is often downregulated by allelic loss or promoter methylation in hepatocellular carcinomas." (PMID 19440376, 2009). "Demethylation treatment of breast cancer cell lines restored expression of DACT1 along with promoter demethylation, as well as in hepatoma cell lines 80, suggesting that promoter methylation is a major mechanism for DACT1 silencing in breast cancer cells." (PMID 35864965, 2022). "DACT1 expression has been shown to be significantly downregulated in hepatocellular carcinoma (HCC), gastrointestinal stromal tumors, non-small cell lung cancer (NSCLC) and breast cancer." (PMID 27708215, 2016). "DACT1 was also reported to be a novel inhibitor of the WNT/β-catenin signaling in hepatocellular carcinoma (HCC)." (PMID 23497530, 2013). "DACT1 is a Wnt-pathway inhibitor, it has been reported that miR-324-3p activated Wnt/β-catenin signaling via targeting DACT1 to promote hepatocellular carcinoma growth, meanwhile, we predicted the binding sites of miR-324-3p in the 3′ non-coding region(UTR) of DACT1 by targetscan." (PMID 32760225, 2020). "DACT1 has been reported to be downregulated in hepatocellular carcinoma." (PMID 22470507, 2012). "However, DACT1 has also been reported to be downregulated in hepatocellular carcinoma and lung cancer, which suggests that the function of DACT1 may be dependent on cellular context." (PMID 22470507, 2012). "In addition, decreased expression and promoter hypermethylation of DACT1 and DACT2 have been found in some primary tumors and tumor cell lines, including hepatocellular carcinoma, breast cancer, lung cancer, colorectal cancer and some other cancers." (PMID 28077137, 2017).
gastric cancer (9 papers, 2016 to 2025). A primary or metastatic malignant neoplasm involving the stomach. "Cyclin G2 inhibited the activity of CKI to phosphorylate DACT1, causing growth arrest in gastric cancer cells." (PMID 35864965, 2022). "Similar antitumor effects of DACT1 have been reported in other malignancies, including breast cancer, lung cancer, gastric cancer, and so on." (PMID 40356725, 2025). "In the present study, DACT1 was found to be highly expressed in gastric cancer cells, suggesting its unique role in gastric cancer." (PMID 40959076, 2025). "In gastric cancer, methylation status of one or more individual CpG sites in genes DACT1, PAX5, and RUNX3 promoter region was also applicable for prognosis." (PMID 29610526, 2018). "Overexpression of DACT1 or ZNF382 in silenced gastric cancer cell lines suppressed colony formation, proliferation and induced cell apoptosis." (PMID 28350359, 2017). "Hypermethylation of the DACT1 DNA promoter was frequently identified to play a regulator of tumorigenesis and prognosis in gastric cancer." (PMID 27833078, 2016). "Finally, based on the expression data of four gene markers (DACT1, EZH2, PAK2, PSPC1), we constructed a staging prediction model for 953 gastric cancer samples (319 early, 497 intermediate, and 137 advanced)." (PMID 40959076, 2025). "It is suggested that cyclin G2 could interact with DACT1 and inhibit the ability of CKI to phosphorylate DACT1, thereby stimulating β-catenin degradation in a GSK-3β-dependent in gastric cancer." (PMID 35864965, 2022). "Dapper homolog 1 (DACT1), a disheveled partner in the planar cell polarity pathway, and a transcription regulator zink finger ZNF382 were found to be frequently silenced in gastric cancer cell lines and in primary gastric cancers via promoter hypermethylation." (PMID 28350359, 2017). "While the mechanism by which CCNG2 inhibits LPR6 and DVL2 in EOC is not known, a recent report in gastric cancer indicated that CCNG2 downregulated DVL2 through the interaction with Dapper1 (DACT1), a Wnt signalling antagonist that has been shown to promote DVL2 degradation." (PMID 31829231, 2019).
breast carcinoma (8 papers, 2013 to 2025). "Promoter CpG methylation of DACT1 was also detected in breast cancer tissues, which was correlated with its downregulation." (PMID 35864965, 2022). "The hypermethylation of DACT1 in the region near TSS within CpG islands was detected in multiple breast cancer cell lines and primary breast tumors, and the methylation status in this region was a main epigenetic mechanism of DACT1 silencing in breast cancer." (PMID 28077137, 2017). "Concordantly, overexpression of DACT1 was observed during the transition of ductal carcinoma in situ to invasive ductal carcinoma in breast cancer." (PMID 27935967, 2016). "Next, increased expression of Dact1 is known to inhibit proliferation of breast cancer cells through inhibition of Wnt/β-catenin signaling, while increased expression of Rgs2 is known to suppress growth of MCF7 and HEK293T breast carcinoma cells." (PMID 26517510, 2015). "The results indicate that promoter methylation is a major mechanism for DACT1 silencing in breast cancer cells." (PMID 23497530, 2013). "DACT1 methylation was detected in 40 (29.9%) of 134 breast cancer tissues, but not in surgical-margin tissues and normal breast tissues, suggesting a tumor-specific methylation of DACT1 in breast cancer." (PMID 23497530, 2013). "We identified DACT1 as a methylated target in the MB231 breast cancer cell line as compared with normal tissue in our pilot cancer epigenome study." (PMID 23497530, 2013). "Reduced expression of active β-catenin and its downstream target gene c-MYC were detected in DACT1-expressing MB231 cells, suggesting that DACT1 antagonizes Wnt/β-catenin signaling by decreasing active β-catenin levels in breast cancer." (PMID 23497530, 2013). "We examined DACT1 expression in breast cancer cell lines and primary tumors with semiquantitative or quantitative RT-PCR and immunochemistry, and further evaluated the promoter methylation of DACT1 with methylation-specific PCR (MSP)." (PMID 23497530, 2013). "Demethylation treatment of breast cancer cell lines restored DACT1 expression along with promoter demethylation, suggesting that an epigenetic mechanism mediates DACT1 silencing in breast cancer." (PMID 23497530, 2013). "Gene-Set Analysis (GSA)-Tumor showed that DACT1 is differently expressed among different subtypes of breast cancer, with relatively high expression in a normal-like subtype (P < 0.00001)." (PMID 23497530, 2013). "DACT1 repression by promoter methylation in breast cancer indicated that DACT1 is likely a tumor suppressor." (PMID 23497530, 2013). "We first examined DACT1 expression in a panel of human normal adult tissues and fetal tissues, as well as breast cancer cell lines, by using semiquantitative RT-PCR." (PMID 23497530, 2013). "We report that DACT1 was frequently methylated in breast cancer cell lines and primary tumors, which was correlated with its downregulation/silencing." (PMID 23497530, 2013). "We further demonstrated the biologic functions of DACT1 in breast cancer cells in vivo and in vitro in the context of the Wnt/β-catenin signaling pathway." (PMID 23497530, 2013). "We also explored the tumor-suppressive functions of DACT1 in vivo and in vitro, and its related mechanism in breast cancer." (PMID 23497530, 2013). "From this study, we report that DACT1 is widely expressed in normal breast tissues but frequently downregulated/silenced by promoter methylation in breast cancer." (PMID 23497530, 2013). "Here, we further examined the expression and promoter methylation of DACT1 in multiple breast cell lines and primary tumors, and evaluated its potential as a tumor biomarker for breast cancer." (PMID 23497530, 2013). "We next analyzed the correlation between DACT1 methylation and clinicopathologic features of breast cancer patients, including age, tumor size, tumor grade, lymph node metastasis, status of estrogen receptor (ER), progestogen receptor (PR), and HER2." (PMID 23497530, 2013).
breast carcinoma (continued). "We found that DACT1 expression was silenced in eight (88.9%) of nine breast cancer cell lines, and its protein levels were obviously reduced in breast tumors compared with paired surgical-margin tissues." (PMID 23497530, 2013). "We found that DACT1 mRNA was obviously downregulated in breast cancer tissues, compared with normal breast tissues (*P < 0.01), as measured with qPCR." (PMID 23497530, 2013). "We further assessed DACT1 expression by using the Gene expression-based Outcome for Breast Cancer Online (GOBO) database." (PMID 23497530, 2013). "Results showed that DACT1 was widely expressed in human normal tissues and fetal tissues, including normal breast tissues, but was frequently silenced or downregulated in breast cancer cell lines studied." (PMID 23497530, 2013). "DACT1 inhibits breast cancer cell proliferation by inducing apoptosis, and further suppresses tumor-cell migration through downregulating β-catenin activity, thus functioning as a tumor suppressor for breast cancer." (PMID 23497530, 2013). "We identified DACT1 as a methylated target in our breast cancer epigenome study." (PMID 23497530, 2013). "Our study demonstrates that DACT1 could function as a tumor suppressor but was frequently downregulated in breast cancer." (PMID 23497530, 2013). "In summary, DACT1, as a Wnt/β-catenin signaling antagonist, is frequently downregulated/silenced in breast cancer, acting as a functional tumor suppressor in breast tumorigenesis, and may serve as a potential tumor marker for breast cancer." (PMID 23497530, 2013). "MSP showed that DACT1 was methylated in five breast cancer cell lines (MB231, MB468, MCF7, T47D, and YCC-B1), although no methylation was found in another two cell lines (SK-BR-3 and ZR-75-1) with silenced DACT1." (PMID 23497530, 2013). "Thus, DACT1 is a functional TSG, inhibiting tumor cell growth and inducing cell apoptosis of breast cancer." (PMID 23497530, 2013). "We found that DACT1, located mainly in the cytoplasm and membrane, reduced the expression of active β-catenin and its downstream target gene c-MYC in breast cancer cells, thus inhibiting cell proliferation of breast cancer by inducing apoptosis, as well as tumor cell migration." (PMID 23497530, 2013). "We observed tumor-specific methylation of DACT1 in breast cancer, indicating its potential as a tumor marker, although no obvious correlation between its methylation and clinicopathologic features was found, which must be further confirmed by a large sample-sized study." (PMID 23497530, 2013).
colon carcinoma (8 papers, 2012 to 2022). "Based on these findings, we hypothesized that DACT1 and the expression levels of membrane-associated β-catenin would be positively correlated in colon cancer cell lines and primary colon cancers." (PMID 22470507, 2012). "In addition, our data showed that the DACT1 expression level and membrane-associated β-catenin expression level were positively correlated in colon cancer cell lines and primary colon cancers." (PMID 22470507, 2012). "To identify the potential roles of DACT1 in the development and progression of colonic carcinoma, we used quantitative real-time PCR (qRT-PCR) to assess the level of gene expression." (PMID 22470507, 2012). "To examine the effects of DACT1 silencing on the invasion of colon cancer cells in vivo, we infected HCT116 cells that expressed a control siRNA or DACT1 siRNA." (PMID 22470507, 2012). "Collectively, these results indicate that DACT1 promotes the proliferation of colon cancer cells by facilitating the transition from the G1 to the S phase of the cell cycle." (PMID 22470507, 2012). "Further studies showed that DACT1 promoted the proliferation of colon cancer cells by facilitating their transition from the G1 to the S phase of the cell cycle." (PMID 22470507, 2012). "Here, we present evidence that DACT1 is an important positive regulator in colon cancer through regulating the stability and sublocation of β-catenin." (PMID 22470507, 2012). "To understand the function of DACT1 in colon cancer, we explored the effect of ectopic DACT1 expression on cellular growth in vitro in cell lines with different levels of endogenous DACT1 expression." (PMID 22470507, 2012). "We have shown that DACT1 promotes cancer cell proliferation in vitro and tumor growth in vivo and enhances the migratory and invasive potential of colon cancer cells." (PMID 22470507, 2012). "Considering that cyclin D1 and c-Myc are related to cell cycle regulation, we examined the effect of DACT1 overexpression and silencing on cell cycle regulation in colon cancer cells." (PMID 22470507, 2012). "Our results showed that the E-cadherin expression pattern in colon cancer cells was unaltered by DACT1 siRNA or DACT1 overexpression." (PMID 22470507, 2012). "Following these results, we conclude that DACT1 enhances anchorage independence in colon cancer cells and their migratory potential." (PMID 22470507, 2012). "The E-cadherin expression pattern in colon cancer cells was unaltered by DACT1 silencing or overexpression." (PMID 22470507, 2012). "The data in the present study support the following model for the mechanism by which DACT1 promotes the oncogenesis of colon cancer cells." (PMID 22470507, 2012). "The results showed that the level of DACT1 mRNA was significantly elevated in all six samples of colon cancer." (PMID 22470507, 2012). "Taken together, our study identifies DACT1 as an important positive regulator in colon cancer and suggests a potential strategy for the therapeutic control of the β-catenin-dependent pathway." (PMID 22470507, 2012). "The results suggest that DACT1 upregulates β-catenin level in colon cancer cells through direct regulation of the multiprotein complex and β-catenin." (PMID 22470507, 2012). "However, DACT1 was reported to be overexpressed in colon cancer and squamous cell carcinoma 40, 41, which indicates that the biological function of DACT1 varies among malignancies." (PMID 35864965, 2022). "DACT1 on the other hand stabilizes β-catenin, leading to disease progression in colon cancer." (PMID 33972406, 2021). "We found that DACT1 upregulated β-catenin in colon cancer cell lines." (PMID 22470507, 2012). "The results confirmed that high levels of DACT1 protein are present in colon cancer." (PMID 22470507, 2012). "However, in this report, we have found that DACT1 is overexpressed in colon cancer, and it acts to enhance cellular proliferation, migration and invasion in colon cancer cell lines." (PMID 22470507, 2012).